STAT3 (signal transducer and activator of transcription 3)
Diseases named in the same sentence as STAT3 in open-access papers (continued):
Sharing a sentence is not in itself a finding about the gene and the disease.
kidney tumor (4 papers, 2013 to 2020). "The relationship between TSC1/TSC2 complex and STAT3 was further confirmed in vivo by assessing the protein and mRNA levels of STAT3 in renal tumors and adjacent normal renal tissues from Tsc2+/- mice." (PMID 31949495, 2020). "Overall, our study indicated that simvastatin could inhibit renal tumor growth in vivo involving the inhibition of AKT, ERK1/2 and STAT3 activity." (PMID 23690956, 2013).
latent infection (4 papers, 2011 to 2023). "Upregulation of Gal-9 promoted the outgrowth and latent infection of EBV-infected B cells, which was linked to B-cell-origin tumors by suppressing STING signaling and subsequently promoting STAT3 phosphorylation." (PMID 36622166, 2023). "For instance, KSHV latent infection in primary endothelial cells resulted in aberrant and chronic activation of STAT3, and activation of STAT3 enhanced KSHV latency." (PMID 27128969, 2016). "However, in 293T-BAC36 cells, in which BAC36 virions have established stable latent infection, it took 30 min of IL-22 treatment for a similar level of STAT3 and ERK 1/2 phosphorylation to occur." (PMID 21544244, 2011).
left ventricular hypertrophy (4 papers, 2016 to 2024). Enlargement of the LEFT VENTRICLE of the heart. "IL-6 is a strong inducer of STAT3 and by inference STAT3 was implicated in left ventricular hypertrophy and dysfunction in this study." (PMID 27899891, 2016). "Detailed mechanisms by which STAT3 interacts with a broad range of cellular and molecular mechanisms to induce left ventricular hypertrophy and heart failure have been discussed in recent review articles, so here we just refer to these excellent reviews." (PMID 30424579, 2018). "Therefore, it is very difficult to separate the effects of hypertension, left ventricular hypertrophy and later systolic heart failure on cardiac STAT3 in preclinical and clinical studies." (PMID 30424579, 2018). "Left ventricular hypertrophy was reduced more by HHP-EXO than CON-EXO via inhibition of β-MHC, BNP, GP130, p-STAT3, p-ERK1/2, and p-AKT." (PMID 36195937, 2022).
leprosy (4 papers, 2013 to 2024). Leprosy is a chronic infectious disease affecting primarily the skin and peripheral nervous system. "We further investigated the requirement for phosphorylation of STAT3 in CCR6+ IL-17A+ cells using flowcytometry in 3 of each leprosy patients." (PMID 27035913, 2016). "SOCS1 known to be a regulator of Th17 differentiation also showed significantly increased expression (p<0.01) in the resistant form of leprosy and supported the increased activation of STAT3 in tuberculoid leprosy." (PMID 23936569, 2013). "In summary, it is evident that RORC was associated with IL-17+ cells and phosphorylated STAT3 rather than total STAT3 expression revealed functional differences in leprosy and was in agreement with the activation by SOCS1." (PMID 23936569, 2013).
myopia (4 papers, 2019 to 2023). "In addition, the STAT3 pathway also induces the alternative activation of macrophages and vascular proliferation which could cause blinding eye disease including high myopia." (PMID 31687416, 2019). "The 6 important intersectional targets of DZP for myopia treatment were STAT3, PIK3CA, PIK3R1, MAPK1, MAPK3, and HSP90AA1." (PMID 37747014, 2023). "Rs12517396 might participate in the STAT3 and TGF-β pathway to influence the development of myopia." (PMID 31687416, 2019).
neuropathic pain (4 papers, 2019 to 2025). Chronic pain caused by damage to nerve fibers. "The STAT3 signaling pathway has been shown to be involved in the activation of astrocytes in neuropathic pain, and spinal STAT3 is phosphorylated and the STAT3 signaling pathway is activated in the neuropathic pain model." (PMID 33225882, 2020). "Altogether, our study showed that TNF-α, via activating STAT3, mediated epigenetic upregulation of Nav1.6 in DRG and contributed to L5-VRT-induced mechanical allodynia, which provided a novel potential target for the treatment of nerve injury-induced neuropathic pain." (PMID 30736806, 2019).
neuropathy (4 papers, 2009 to 2024). A disorder affecting the nervous system that manifests with pain, tingling, numbness, and/or muscle weakness. "In a murine model, administration of bortezomib, a proteasome inhibitor, in dorsal root ganglion induced painful neuropathy by phosphorylating signal transducer and activator of transcription-3 (STAT3) and acetylation of histone H3 and H4 in the NLRP3 promoter region." (PMID 38421496, 2024). "A previous study indicated that C3ar1 regulates the expression of STAT3 and mediates inflammation during neuropathy, which is not clear in the retina." (PMID 36110094, 2022).
NK/T-cell lymphomas (4 papers, 2017 to 2022). "We propose that the STAT3-D427H mutation has, if any, only a mild impact on the etiology of NK/T-cell lymphomas." (PMID 35752777, 2022). "The missense mutation D427H localized in the STAT3 DNA-binding domain has been previously reported in patients with NK/T cell lymphomas." (PMID 35752777, 2022). "Recent studies have shown that activating mutations to STAT3 frequently occur in NK/T-cell lymphomas, which are dependent on STAT3 activity for growth." (PMID 29228628, 2017). "Although the STAT3-D427H mutation has been reported in the pathogenesis of NK/T-cell lymphoma, it is unlikely that the sole presence of this mutation could significantly increase the oncogenic potential of the STAT3 molecule." (PMID 35752777, 2022). "Activating STAT3 mutations E616G and E616K in the SH2 domain found in NK/T cell lymphoma patients were shown to increase the phosphorylation and transcriptional activity of STAT3." (PMID 31963765, 2020). "Based on these findings, we conclude that STAT3-D427H may not have an oncogenic potential that exceeds the WT protein and may have little significance or an ancillary role in the pathogenesis of NK/T-cell lymphomas." (PMID 35752777, 2022).
papilloma (4 papers, 2013 to 2017). A benign epithelial neoplasm that projects above the surrounding epithelial surface and consists of villous or arborescent outgrowths of fibrovascular stroma. "We show that TC-PTP-deficient mice develop papillomas more quickly than wild-type control mice and this result corresponds with an increase in phosphorylated STAT3 expression." (PMID 28322331, 2017). "In a two-stage carcinogenesis experiment, tamoxifen treatment prior to DMBA treatment of inducible Stat3-deficient mice significantly delayed tumor onset and reduced the number of papillomas per mouse." (PMID 23577258, 2013). "In addition, papillomas from TC-PTP KO mice had significantly higher levels of phosphorylated STAT3 and phosphorylated AKT expression when compared with control." (PMID 28322331, 2017). "Inhibition of Stat3 using an oligonucleotide decoy targeting Stat3 inhibited TPA-induced papilloma formation in TG.AC mice, confirming that Stat3 is required for the clonal expansion of initiated cells during the promotion phase of two-stage skin carcinogenesis." (PMID 23577258, 2013). "Using this inducible model, Stat3 deletion at the time of initiation in bulge region keratinocytes led to a significant reduction in tumor incidence and multiplicity (~80% reduction in papilloma formation)." (PMID 23577258, 2013). "The K15.CrePR1 inducible system is not 100% efficient and the small number of papillomas obtained from these knockout mice stained positive for Stat3." (PMID 23577258, 2013).
peripheral arterial disease (4 papers, 2021 to 2024). A disorder of the arteries supplying the upper and lower extremity and the visceral organs. "This is of interest as in a model of peripheral arterial disease, autocrine IL-1β signalling promoted transcription of pro-angiogenic VEGF via activation of STAT3 and NF-kB." (PMID 38480935, 2024).
respiratory infections (4 papers, 2021 to 2025). "Beyond MP, the IL-6/STAT3 pathway has been implicated in a variety of other pediatric respiratory infections." (PMID 41137299, 2025).
rheumatic diseases (4 papers, 2018 to 2022). "Previously, we have also demonstrated that miRNA-135b targeting STAT3 is reduced in other rheumatic diseases including SSc." (PMID 29744553, 2018). "Nonfunctional STAT3 may lead to serious illnesses, such as cancer, rheumatic diseases, and diseases of aging, but regulation of JAK2/STAT3 by the humanin pathway has anti-oxidant effects." (PMID 35986247, 2022).
Right ventricular hypertrophy (4 papers, 2021 to 2025). In this case the right ventricle is more muscular than normal, causing a characteristic boot-shaped (coeur-en-sabot) appearance as seen on anterior- posterior chest x-rays. "This broke the STAT3-miR-204-STAT3 feed-forward cycle, shifted the balance to an antiproliferative state, and improved PH, right ventricular hypertrophy, and pulmonary vascular remodeling." (PMID 36419957, 2022). "The data obtained in this study showed that the expression of p-STAT3 in IL-17-deficient mice RV tissue was downregulated, indicating that IL-17 may induce right ventricular hypertrophy through activating STAT3." (PMID 34020615, 2021).
serous carcinoma (4 papers, 2016 to 2022). "Increased expression of pY-STAT3 in association with loss of protein inhibitor of activated STAT3 (PIAS3) resulted in the progression of high-grade serous carcinoma." (PMID 35401182, 2022). "Rosen found an association between p-STAT3 expression and poorly differentiated (75%), clear cell (73%), and serous carcinoma (63%) histotypes (p = 0.01) but not with any of the other clinicopathologic variables tested." (PMID 34789292, 2021).
tongue tumors (4 papers, 2015 to 2025). "Morphometric and immunohistochemical analysis found that P. gingivalis chronic infection markedly enhanced the severity of the tongue tumours; STAT3 controls crucial genes driving proliferation, suppression of apoptosis, and aggressive tumour behaviour through the upregulation of cyclin D1." (PMID 41228271, 2025).
Uterine leiomyoma (4 papers, 2022 to 2025). The presence of a leiomyoma of the uterus. "The findings indicate that STAT-3 and IL-26 are significantly increased in uterine leiomyoma tissue, and that this increase may be associated with various cellular mechanisms that promote tumor growth." (PMID 40943781, 2025). "In contrast, we observed an increased number of smooth muscle and fibroblast cells showing strong STAT-3 positivity in the uterine leiomyoma sections." (PMID 40943781, 2025). "Further translational and clinical research on human tissues is needed to elucidate the role of STAT-3 in the pathogenesis of uterine fibroids." (PMID 40943781, 2025). "miR-29 inhibitors promoted protein expression of STAT-3, Cyclin D1, and c-Myc compared with the anti-NC control (P < 0.01), and miR-29 inhibitors promoted cell proliferation in uterine leiomyoma cells (P < 0.05)." (PMID 35113040, 2022). "The main results of this study were that the expression of miR-29 was lower in uterine leiomyoma, and the expression of STAT3 was up-regulated in uterine leiomyoma." (PMID 35113040, 2022). "Basic cell experiments were used to explore the potential regulatory mechanism of miR-29b on STAT3 in uterine leiomyoma to provide basic research for clinical treatment." (PMID 35113040, 2022). "In future studies, pharmacologically targeting cytokine signaling pathways, such as STAT-3 or IL-26, may offer a potential treatment option to control the growth of uterine fibroids, which are very common in women of reproductive age." (PMID 40943781, 2025). "Activation of JAK2/STAT3, MAPK/ERK, and PI3k/Akt pathways have previously been linked to the binding of leptin, an adipocyte derived hormone, to Ob-R; however, the effect of adipocyte coculture on uterine leiomyoma cells remained a gap in knowledge." (PMID 36771423, 2023). "This study explores the mechanism of miR-29 and STAT3 signaling pathways on uterine leiomyoma." (PMID 35113040, 2022). "In conclusion, the high expression of miR-29 can inhibit cell proliferation, invasion, and metastasis in uterine leiomyoma, which might be related to the inhibition of the STAT3 signaling pathway." (PMID 35113040, 2022). "The significant role of miR-29 and STAT3 in uterine leiomyoma was verified using public data sets." (PMID 35113040, 2022). "One research showed that STAT3 could increase the expression of Cyclin D1 and c-Myc, and promote the proliferation of uterine leiomyoma cells." (PMID 35113040, 2022). "When miR-29 was not inhibited, it could bound to STAT3 and led to the degradation of STAT3, thereby reducing the expression of Cyclin D1 and c-Myc and inhibiting the proliferation of uterine leiomyoma cells." (PMID 35113040, 2022). "In this study, we examined the levels of STAT-3 and IL-26 expression in samples obtained from patients with leiomyoma uteri and patients who underwent hysterectomy for benign reasons and evaluated the possible role of this transcription factor in the pathogenesis of uterine fibroids." (PMID 40943781, 2025). "For the first time, we demonstrated the amplified activation of JAK2/STAT3, MAPK/ERK, and PI3k/Akt because of adipocyte coculture along with leptin treatment in uterine leiomyoma cells." (PMID 36771423, 2023). "The upregulation of the JAK2/STAT3, MAPK/ERK, and PI3k/Akt pathways impacts several pathways integral to cell growth and metabolism and implicates adipose tissue as having a role in the cancerous uterine leiomyoma growth." (PMID 36771423, 2023). "Using MCODE, we found that STAT3, VEGFA, CCND1, and other genes were the hub genes of uterine leiomyoma, proving that they might play a significant role in the pathogenesis and progression uterine leiomyoma." (PMID 35113040, 2022). "However, it is not clear whether miR-29 could target STAT3 to regulate the biological characteristics of cell proliferation and invasion in uterine leiomyoma." (PMID 35113040, 2022).
viral hepatitis (4 papers, 2018 to 2022). An acute or chronic inflammation of the liver parenchyma caused by viruses. "Furthermore, aberrantly expressed STAT3 was also associated with viral hepatitis." (PMID 34307193, 2021).
Abdominal obesity (3 papers, 2013 to 2021). Excessive fat around the stomach and abdomen. "A high dietary saturated fatty acid intake amplifies the genetic predisposition to abdominal obesity which connected with certain STAT3 genotypes." (PMID 34835928, 2021). "STAT3 protein is thought to be an important factor associated with increased risk of abdominal obesity." (PMID 34835928, 2021). "Common genetic variants at the STAT3 locus have recently been associated with increased risk of abdominal obesity." (PMID 23306188, 2013). "Polymorphism in the STAT3 gene might interact with higher saturated fat intake and increases the risk of abdominal obesity." (PMID 33302351, 2020). "High dietary SFA intake (≥15.5% of energy) modulated the genetic association between STAT3 polymorphisms with obesity; carriers of more than 2 risk alleles with the highest SFA consumption further increased their risk of abdominal obesity by 32% compared to those carrying one or fewer risk alleles." (PMID 23306188, 2013).
abortion (3 papers, 2015 to 2023). the ending of pregnancy by removing a fetus or embryo before it can survive outside the uterus. "Both STAT3 and TCF4 are downregulated in the decidua of patients with recurrent spontaneous abortion compared with those with normal pregnancy." (PMID 36982674, 2023).
acne (3 papers, 2024 to 2025). An inflammatory process of the sebaceous glands which is characterized by comedones, nodules, papules and/or pustules on the skin. "A total of 37 potential targets were predicted by network pharmacology, among which TNF, IL-1B, IL-6, ESR1, PPARG, NFκB1, STAT3, and TLR4 may be the key targets of GA in the treatment of acne." (PMID 38792208, 2024).
Acute hepatitis (3 papers, 2007 to 2019). Acute hepatic injury resulting from inflammation typically accompanied by increased serum alanine transaminase activity. "Notch signaling enhanced IL-22 production by CD4+ T cells even in absence of STAT3 by stimulation of AhR in a ConA-mediated acute hepatitis model in RBP-J−/− mice." (PMID 27800305, 2016). "As the amount of STAT3-Tyr phosphorylation indicates the DNA binding capacity of the protein, the pathways seems to be activated in fibrotic diseases and not in acute hepatitis." (PMID 17672890, 2007).
age-related macular degeneration (3 papers, 2016 to 2021). Age-related loss of vision in the central portion of the retina (macula), secondary to retinal degeneration. "Previously, we have shown that STAT3 activation in circulating immune cells contributes to the pathogenesis of neovascular age-related macular degeneration." (PMID 31286987, 2019). "In these studies, investigators found that IL-10 activation of STAT3 in macrophages promotes choroidal neovascular angiogenesis, an important pathological event in blindness, resulting from some forms of age-related macular degeneration." (PMID 27491076, 2016). "Administration of the small molecule, 5,15-di phenyl porphyrin (DPP), a selective inhibitor of IL-10/STAT3 signaling, has been shown to reduce pathologic neovascularization and Age-related Macular Degeneration (AMD) via inhibition of alternative activation and M2 polarization of macrophages." (PMID 34777338, 2021).
allergic conjunctivitis (3 papers, 2023 to 2025). "Gp130 can promote allergic conjunctivitis by increasing the phosphorylation levels of JAK2 and STAT3." (PMID 40005151, 2025).
apical periodontitis (3 papers, 2022 to 2025). "Our study investigating human apical periodontitis lesions, including PGs and RCs, identified ZEB1 as a potential participant associated with STAT3 activation and Th17 cells in the pathogenesis of apical periodontitis." (PMID 40016707, 2025). "The study aimed to investigate the expression pattern of ZEB1 in Th17 cells and its colocalization with p-STAT3 in human apical periodontitis lesions." (PMID 40016707, 2025). "This study revealed that ZEB1 is a potential player correlated with STAT3 activation and Th17 cells in apical periodontitis pathogenesis." (PMID 40016707, 2025).
arteriosclerosis (3 papers, 2021 to 2025). A vascular disorder characterized by thickening and hardening of the walls of the arteries. "Meanwhile, the abnormal activation of the IL6/JAK/STAT3 pathway can upregulate VCAM-1, accelerate endothelial cell damage, and promote arteriosclerosis." (PMID 40809841, 2025).